NPM1 (nucleophosmin 1)
Diseases named in the same sentence as NPM1 in open-access papers (continued):
Sharing a sentence is not in itself a finding about the gene and the disease.
breast carcinoma (continued). "The expression of NPM1 is upregulated in breast cancer, and the acetylation and succinylation of NPM1 may lead to a DNA damage response by regulating the chromosome structure, thus affecting the development of breast cancer." (PMID 36397343, 2022). "The expression of NPM1 in breast cancer was lower than that in normal tissues." (PMID 34335635, 2021). "In addition, SIRT7 participates in ageing processes and breast cancer lung metastasis by deacetylating nucleophosmin (NPM1) and SMAD4." (PMID 34129782, 2021). "Higher NPM1 expression has been found in the serum samples of breast cancer patients." (PMID 32257110, 2020). "Additionally, NPM1 expression was positively correlated with PD-L1 expression in breast cancer patients." (PMID 32245950, 2020). "Some results support a tumor-suppressive role for NPM1 in breast cancer." (PMID 25779011, 2015). "Furthermore, NPM1 silencing can impede cell cycle progression in breast cancer cells." (PMID 40705480, 2025). "Notably, a recently published study showed that NPM1 could regulate the expression of programmed cell death-ligand 1 (PD-L1) at the transcriptional level and promote breast cancer progression." (PMID 37875480, 2023). "First, we confirmed the interaction between PARP1 and NPM1 protein in ESCC cells, which is consistent with previous findings in breast cancer cells." (PMID 39367700, 2024). "NPM1 has been reported to epigenetically regulate PD-L1 expression in breast cancer, and once bound to poly (ADP-ribose) polymerase-1 (PARP1), NPM1 loses the ability to activate PD-L1." (PMID 37875480, 2023). "In summary, we have identified NPM1 as a transcriptional regulator of PD-L1, which particularly promotes PD-L1 expression in TNBC, and is correlated with poor prognosis in breast cancer." (PMID 32245950, 2020). "Though ER−/PR−/HER-2− breast cancers are all defined as TNBCs, there are different biological behavior, clinical features, therapeutic response and driver genes among them, and the function of NPM1 in regulating PD-L1 expression may be related to the subtypes of TNBCs." (PMID 32245950, 2020). "APE1 and its regulatory factor NPM1 could also reduce the cytotoxicity of platinum-based chemotherapy drugs to triple-negative breast cancer cells, and reduced levels of APE1 in breast cancer cells could improve its sensitivity to olapalil." (PMID 38977966, 2024). "Although NPM1 was not an independent prognostic factor based on our COX-regression analysis, our analysis showed that patients with negative hormone receptor expression tended to have higher level of NPM1, suggesting that NPM1 still had prognostic value in breast cancer treatment." (PMID 32245950, 2020).
Myelodysplasia (30 papers, 2014 to 2026). Clonal hematopoietic stem cell disorders characterized by dysplasia (ineffective production) in one or more hematopoietic cell lineages, leading to anemia and cytopenia. "Based on these findings, it was suggested that NPM1 mutation plays a pivotal role in myelodysplasia development." (PMID 38398096, 2024). "As such, the presence of del(9q) was also removed as a defining myelodysplasia-related cytogenetic abnormality because its association with NPM1 and biallelic CEBPA mutations." (PMID 32722092, 2020). "These non-acute MNs have also been regarded as early stage AML, due to a mutational profile with fewer myelodysplasia-related gene mutations, their sensitivity to chemotherapy, the eradication of NPM1 following intensive treatment and its reappearance at relapse." (PMID 38398096, 2024). "Consequently, we compared outcome of the NPM1-mutated/FLT3-ITD-negative patients who carried myelodysplasia-related mutations with outcome of patients included in the 2022 ELN intermediate group." (PMID 36823396, 2023). "However, the presence of myelodysplasia-related mutations in NPM1-mutated/FLT3-ITD-negative patients portended worse outcome, which placed these patients firmly in the 2022 ELN intermediate, not favorable, group." (PMID 36823396, 2023). "All these patients had mutated NPM1 with a low allele ratio of FLT3-ITD, three patients also had one or more myelodysplasia-related gene mutations, and one patient also had a biallelic but non-bZIP CEBPα mutation." (PMID 38609396, 2024). "Moreover, 68 patients (25,8%) had AML with nucleophosmin (NPM1) mutation and 54 patients (20%) had AML with myelodysplasia-related changes." (PMID 35805006, 2022). "Nevertheless, controversial issues include the percentage of blasts required for the diagnosis of NPM1-mutated AML and whether cases of NPM1-mutated myelodysplasia and chronic myelomonocytic leukaemia do exist." (PMID 33879827, 2021). "This change was based on emerging data showing that multilineage dysplasia in the absence of myelodysplasia-related cytogenetic changes did not appear to associate with poor prognosis in the presence of an NPM1 mutation or biallelic CEBPA mutation." (PMID 32722092, 2020). "FLT3-ITD, NPM1, and IDH1/2 were the most mutated genes, while also high proportion of ASXL1 and RUNX1 mutations could be detected, indicating the high proportion of myelodysplasia-related AML." (PMID 39453477, 2025). "The newer guidelines also outline that NPM1-mutated AML with concurrent adverse-risk cytogenetic changes are linked to adverse risk, while research is ongoing regarding the implications of other abnormalities, such as myelodysplasia-related mutations, when paired with mutated NPM1." (PMID 36498870, 2022). "CPX did not provide a survival benefit in patients with myelodysplasia (MDS)-related mutations and was associated with poorer survival in patients with NPM1 (HR, 2.83) and FLT3 mutations (HR, 2.14)." (PMID 41237344, 2026).
Myelodysplasia (continued). "Among favorable-risk patients, myelodysplasia-related mutations did not affect patients with CEBPAbZIP mutations or core-binding factor AML, but changed risk assignment of NPM1-mutated/FLT3-ITD-negative patients to intermediate." (PMID 36823396, 2023).
colon cancer (23 papers, 2007 to 2025). "The finding of increased expression and activity of NPM1 in BRAF-mutated colon cancer prompted us to examine its potential role in modulating the response and resistance to BRAFV600E inhibitor vemurafenib." (PMID 34201061, 2021). "NPM1 expression was reported to be increased in colon cancer and associated with lymph node metastasis." (PMID 34503224, 2021). "Findings from this study point to the therapeutic potential of targeting the NPM1/c-Myc axis in BRAF-mutated colon cancer and provide a framework to devise novel strategies for counteracting the resistance to BRAF inhibition in colon cancer." (PMID 34201061, 2021). "We observed a trend towards an increased basal expression of the NPM1 protein in BRAF-mutated colon cancer cell lines in comparison with the cells carrying either WT BRAF/mutant KRAS or double WT BRAF/KRAS." (PMID 34201061, 2021). "On the other hand, NPM1 overexpression was associated with the presence of distant metastasis in colon cancer." (PMID 24410879, 2014). "Increased expression of NPM1 was also found to be associated with lymph node metastasis and poor survival of colon cancer patients." (PMID 22631075, 2012). "NPM1 has also been found to be associated with the progression of various human solid tumors, such as hepatocellular carcinoma, colon cancer, and prostate cancer, among other oncological diseases 29-31, and high levels of NPM1 can be observed in cancer tissue compared to paraneoplastic tissue." (PMID 38164189, 2024). "Collectively, findings from this study provide ample indication that the NPM1/c-Myc axis could represent a promising therapeutic target to thwart resistance to vemurafenib in BRAF-mutated colon cancer." (PMID 34201061, 2021). "Furthermore, analysis of the mRNA expression profile data from colon adenocarcinoma patients in the TCGA database revealed significant up-regulation of the NPM1 gene in BRAFV600E-mutated colon cancer." (PMID 34201061, 2021). "Statistical analysis showed that the overexpression of NPM1 was associated with distant metastasis, suggesting that NPM1 might play a critical role in colon carcinogenesis and colon cancer metastasis." (PMID 22631075, 2012). "For instance, inhibiting NPM1 reduces the proliferation, migration, and invasion of lung adenocarcinoma cells and colon cancer cells." (PMID 40705480, 2025). "Correlation of higher NPM1 expression with LN metastasis was also found in patients with oral squamous carcinoma and colon cancer." (PMID 37142981, 2023). "Small interfering RNA (siRNA) of NPM1 inhibited migration and invasiveness of metastatic colon cancer in the HCT116 cell line." (PMID 37142981, 2023). "In a variety of solid tumors (gastric cancer, colon cancer, and thyroid cancer), NPM1 overexpression can directly participate in tumorigenesis, and the expression level of NPM1 is positively correlated with tumor development stage." (PMID 36280841, 2022). "Here, we have shown that an increased basal expression of NPM1 in BRAF mutant colon cancer cell lines coincides with an increased expression level of phospho-c-Myc (Ser62)." (PMID 34201061, 2021). "Since many of these proteins including NPM1, RanBP1, eIF4E and PSPH were previously reported to be transcriptional targets of c-Myc, expression of c-Myc in colon cancer cell lines differing in their BRAF mutational status was also examined." (PMID 34201061, 2021). "High expression of NPM1 was previously shown to correlate with lymph node metastasis in colon cancer patients and to promote in vitro colon cancer cell proliferation, migration and invasion." (PMID 34201061, 2021). "One of these factors is Nucleophosmin 1 (B23), which is upregulated in adenomas and cancers of the colon and translocates from the nucleolus to the nucleoplasm upon SIPS." (PMID 29218300, 2017). "High-expression of NPM1 correlates with lymph node metastasis (P = 0.0003) and poor survival rate of human colon cancer patients (P = 0.017)." (PMID 22631075, 2012).
colon cancer (continued). "The expression level of NPM1 in 31 groups of colonic carcinoma tissues, including colon tumors, adjacent normal tissues, and matched metastatic lymph nodes from the same patients was investigated." (PMID 22631075, 2012). "Immunohistochemical assay was performed to examine the expression pattern of NPM1 in 31 groups of colonic carcinoma samples, including colon tumors, adjacent normal tissues, and matched metastatic lymph nodes from the same patients." (PMID 22631075, 2012). "In the current study, the expression pattern of NPM1 in colon cancer tissues and adjacent normal tissues was examined." (PMID 22631075, 2012). "The current finding on the increased expression of NPM1 in highly metastatic HCT116 colon cancer cells probably indicate that NPM1 is involved in colon cancer metastasis, in addition to cell growth regulation and proliferation." (PMID 22631075, 2012). "The current results suggested that the elevated expression of NPM1 correlated with distant metastasis and poor survival of colon cancer patients." (PMID 22631075, 2012). "The current study also provided the first direct evidence that the expression level of NPM1 is critical for colon cancer cell migration and invasion." (PMID 22631075, 2012). "We aimed to examine the expression level of Nucleophosmin (NPM1) protein in colon cancer tissues and to investigate the potential role of NPM1 in the regulation of cell migration and invasiveness." (PMID 22631075, 2012). "In the current study, evidence that NPM1 expression was remarkably increased in the colon cancer tissues and metastatic lymph nodes compared with the adjacent noncancerous tissues was provided." (PMID 22631075, 2012). "Migration and invasion is critical for cancer cell metastasis, thus, the current results provided direct evidence that the expression level of NPM1 is necessary for colon cancer cell metastasis." (PMID 22631075, 2012). "Moreover, through database mining, it was found that PD-L1 and NPM1 expression were positively correlated in both colon cancer and skin cutaneous melanoma." (PMID 38243170, 2024). "Further along this line, loss of INPP4B significantly inhibited proliferation of NPM1-mutated OCI-AML3 cells, and overexpression of INPP4B enhanced proliferation of melanoma cells and melanocytes as well as colon cancer cells, in which INPP4B acts as an oncogenic driver." (PMID 36993823, 2023). "Another study uncovered the critical role of NPM1 in the regulation of colon cancer cell migration and invasion, and NPM1 may serve as a potential marker for the prognosis of colon cancer patients." (PMID 25779011, 2015). "In addition, a positive correlation was also found between the high expression of NPM1 and the poor five-year survival performance of colon cancer patients." (PMID 22631075, 2012). "In support of this hypothesis, the present results showed that siRNA induced the down-regulation of NPM1-inhibited migration and invasion of human colon cancer cell HCT116 along with decreased cell proliferation." (PMID 22631075, 2012). "The current study uncovered the critical role of NPM1 in the regulation of colon cancer cells migration and invasion, and NPM1 may serve as a potential marker for the prognosis of colon cancer patients." (PMID 22631075, 2012). "Importantly, our analysis also confirmed several well-characterized shared neoantigens, including AVEEVSLRK derived from an NPM1 frameshift mutation in AML, SLMEQIPHL from a CKAP2 frameshift mutation in colon cancer, and 37 private neoantigens now deposited in the IEDB database." (PMID 40672284, 2025). "In conclusion, we found that NPM1 expression and activity potentially associated with the regulation of centrosome duplication and mitotic progression are specifically increased in BRAFV600E mutant colon cancer cells and tumor tissues from BRAF-mutated colon adenocarcinoma patients." (PMID 34201061, 2021).
colon cancer (continued). "Nucleophosmin (NPM1) is a protein biomarker that can reflect the therapeutic effect of chemotherapy, which not only has the function of monitoring the progression in hematological diseases, but also has differential expression in some solid tumors such as colon cancer and lung adenocarcinoma." (PMID 32411234, 2020). "Although the detailed mechanism of NPM1 in colon carcinogenesis remains to be elucidated, the present study speculated that NPM1 may be a potential prognosis biomarker and a possible therapeutic target for colon cancer patients." (PMID 22631075, 2012). "To investigate the role of NPM1 in CAC development, we subjected WT mice and Npm1+/− mice to an azoxymethane (AOM)/DSS colon tumor model." (PMID 39103576, 2024). "Therefore, NPM1 may play a role in the enhanced invasiveness of colon cancer cells." (PMID 22631075, 2012). "Thus, high NPM1 expression may be a poor prognosis marker for colon cancer patients." (PMID 22631075, 2012). "Given the central regulatory roles of NPM1 and c-Myc in these processes, their targeting could provide novel opportunities to counteract drug resistance in BRAF mutant colon cancer." (PMID 34201061, 2021). "In addition, the exogenous expression of NPM1 in HT29 cells, a NPM1 low expression and low invasive colon cancer cell line, enhanced cell migration and invasiveness along with increased cell proliferation." (PMID 22631075, 2012).
lung carcinoma (23 papers, 2018 to 2024). "Beyond PC, one of the identified hub genes, NPM1, has significant associations with glycolysis in lung cancer and pancreatic cancer." (PMID 38794139, 2024). "A recent work from Cho and collaborators reported that Puf‐A promotes non‐small cell lung cancer (NSCLC) progression by the interaction with nucleophosmin (NPM1) in the nucleolus." (PMID 39465903, 2024). "One study showed that overexpression of DNAJB4 indirectly upregulated the expression of E-cadherin or regulated the complex formation of NPM1 and inhibited cell invasion and migration in highly invasive lung cancer." (PMID 37510314, 2023). "The phenotypes include nucleophosmin 1 (NPM1) expression in lung cancer, eukaryotic translation initiation factor 2 Subunit β (EIF2S2) expression in colorectal cancer, and methyltransferase 3 (METTL3) expression in ESCA." (PMID 35794622, 2022). "DNMT3A mutation happened in a variety of cancers such as colorectal cancer, lung cancer, chronic myelocytic leukemia, but is mainly with AML and usually occur with other types of mutations, such as FLT3, NPM1, C/EBP alpha, resulting in synergistic effects in AML." (PMID 36303144, 2022). "TGP18 (1 μM) treatment indeed influenced NPM1 nuclear localization within A549 lung cancer cells." (PMID 32929356, 2020). "We also found several recurrent ALK fusions which have not been reported in lung cancer, but have been identified in other cancer types, such as VCL-ALK, FN1-ALK, and NPM1-ALK." (PMID 34508169, 2021).
T-cell lymphoma (22 papers, 2013 to 2025). "TET2 and NPM1 mutations are markedly associated with DNMT3A mutations in T-cell lymphoma and adult AML, respectively." (PMID 23946816, 2013). "In contrast, ALK+ALCL, a kind of T-cell lymphoma, typically involves the NPM1-ALK or TPM3-ALK fusion gene." (PMID 29747676, 2018). "This includes anaplastic large-cell lymphoma with NPM1-ALK (anaplastic lymphoma kinase) and T-cell lymphoma with NPM1-TYK2 (tyrosine kinase 2)." (PMID 36834572, 2023). "Although a reciprocal regulatory relationship was established between STAT5A and a NPM–ALK fusion protein in T-cell lymphoma, no direct connection between STAT5 and wild-type NPM1 has been documented." (PMID 28005077, 2016).